DENND5B (DENN domain containing 5B)
Description:
Guanine nucleotide exchange factor (GEF) which may activate RAB39A and/or RAB39B. Promotes the exchange of GDP to GTP, converting inactive GDP-bound Rab proteins into their active GTP-bound form.
Synonyms: MGC24039
Tractability: Antibody: UniProt predicts a signal peptide or a membrane-spanning region. PROTAC: ubiquitination databases record sites on it; its protein half-life has been measured.
Gene: Protein-coding gene on chromosome 12 (31,382,226 to 31,591,170, reverse strand). Ensembl gene ENSG00000170456.
Subcellular location: Membrane
Subcellular location (Human Protein Atlas): Microtubules
Pathways (Reactome):
Vesicle-mediated transport: RAB GEFs exchange GTP for GDP on RABs
Gene Ontology:
Molecular function: guanyl-nucleotide exchange factor activity; small GTPase binding
Biological process: positive regulation of triglyceride transport
Cellular component: cytosol; membrane
Genetic constraint (gnomAD): Loss-of-function variants: 34 observed, 128.92 expected, observed/expected ratio (o/e) 0.26, 90% interval 0.2 to 0.35. The upper end of that interval is the gene's LOEUF score, 0.35, which puts it in group 1 of 6, group 1 being the genes least tolerant of losing a copy. Missense variants: 1,139 observed, 1,531.6 expected, observed/expected ratio (o/e) 0.74, 90% interval 0.71 to 0.78. Synonymous variants: 551 observed, 560.54 expected, observed/expected ratio (o/e) 0.98, 90% interval 0.92 to 1.05.
Gene-disease validity (ClinGen):
ClinGen rates the evidence that DENND5B causes each of these diseases.
complex neurodevelopmental disorder (autosomal dominant): Limited. A disorder that involves more than one phenotype associated with the central nervous system, including but not limited to intellectual disability, autism, and seizures (epilepsy).
Homologues: Orthologues: macaque DENND5B (99% identical), pig DENND5B (98% identical), dog DENND5B (97% identical), chimpanzee DENND5B (97% identical), mouse Dennd5b (95% identical), rat Dennd5b (95% identical), rabbit DENND5B (93% identical), guinea pig DENND5B (92% identical), tropical clawed frog dennd5b (86% identical), zebrafish dennd5b (76% identical). Paralogues in human: DENND5A (72% identical), PKD1 (17% identical), PKDREJ (14% identical), PKD1L1 (14% identical), PKD1L2 (13% identical), LOXHD1 (12% identical), PKD1L3 (10% identical), PKD2L1 (8% identical), PKD2 (8% identical), PKD2L2 (6% identical).
Diseases named in the same sentence as DENND5B in open-access papers:
DENND5B is named in the same sentence as 26 diseases in open-access papers, as found by Europe PMC text mining. Sharing a sentence is not in itself a finding about the gene and the disease. The quoted sentences say what the papers report.
atherosclerosis (2 papers, 2019 to 2022). A disease characterized by the build-up of fatty material and calcium deposition in the arterial wall resulting in partial or complete occlusion of the arterial lumen. "It is still unclear if the protective effect of Dennd5b deficiency on atherosclerosis is a direct consequence of impaired absorption of dietary cholesterol or potentially a result of secondary effects of Dennd5b on hepatic lipid metabolism." (PMID 36243100, 2022). "There is also evidence of a possible association of DENND5B variants and atherosclerosis in humans." (PMID 30837651, 2019). "By influencing plasma lipids and body weight, DENND5B might be expected to affect cardiovascular disease risk, specifically atherosclerosis." (PMID 30837651, 2019). "As a consequence, Dennd5b−/− mice are resistant to diet-induced obesity, hypercholesterolemia, and atherosclerosis." (PMID 36243100, 2022). "Atherosclerosis quantified by en face analysis and in aortic root sections, revealed significantly smaller lesions in Dennd5b−/− compared to Dennd5b+/+ mice." (PMID 36243100, 2022). "This study examined the impact of whole-body Dennd5b deletion on plasma lipid concentrations, atherosclerosis, and hepatic lipid metabolism in mice." (PMID 36243100, 2022). "Our findings reveal that Dennd5b−/− mice are resistant to PCSK9-induced hypercholesterolemia and atherosclerosis." (PMID 36243100, 2022).
cervical cancer (2 papers, 2022 to 2024). A primary or metastatic malignant neoplasm involving the cervix. "We expressed WT and DENND5B mutants into two cell lines having different cell background: HeLa (derived from a cervical cancer) and CFPAC-1 (derived from a ductal pancreatic adenocarcinoma)." (PMID 38387458, 2024).
Hypercholesterolemia (2 papers, 2022 to 2024). An increased concentration of cholesterol in the blood. "We hypothesized that reduced absorption of dietary lipids in Dennd5b−/− mice would result in peripheral effects on lipid metabolism and atherosclerotic vascular disease but that PCSK9-induced hypercholesterolemia would overcome the protective effect of Dennd5b deficiency." (PMID 36243100, 2022). "Furthermore, it has been observed that Dennd5b–/– mice demonstrate resistance to weight gain induced by dietary intake and exhibit reduced susceptibility to PCSK9-induced hypercholesterolemia." (PMID 39649955, 2024). "Compared to Dennd5b+/+ mice, Dennd5b−/− mice were resistant to diet-induced weight gain and PCSK9-induced hypercholesterolemia." (PMID 36243100, 2022).
Intellectual disability (2 papers, 2023 to 2026). "Furthermore, seven intellectual disability candidate genes, TM7SF3, STK38L, ARNTL2, ERGIC2, TMTC1, DENND5B and ETFBKMT have been identified." (PMID 37034680, 2023).
anxiety disorder (1 paper, 2026). A category of psychiatric disorders which are characterized by anxious feelings or fear often accompanied by physical symptoms associated with anxiety. "Heterozygous de novo variants in DENND5B with predicted loss of function have been associated with neurodevelopmental disorders with dysmorphic features and behavioral dysregulation (the latter including ASD, ADHD, and anxiety disorder)." (PMID 41595523, 2026).
aortic atherosclerosis (1 paper, 2019). A atherosclerosis that involves the aorta. "In mice, loss of Dennd5b results in resistance to western diet induced obesity, changes in plasma lipids, and reduced aortic atherosclerosis." (PMID 30837651, 2019).
colorectal cancer (1 paper, 2021). A primary or metastatic malignant neoplasm that affects the colon or rectum. "Dennd5b was identified as a prognostic biomarker in colorectal cancer and is involved in the regulation of intestinal triglyceride absorption and body weight." (PMID 34956935, 2021).
diabetes (1 paper, 2024). "Our investigation has provided preliminary evidence suggesting a causal relationship between the DENND5B gene and diabetes-peripheral artery disease (DM-PAD), highlighting their significance in the etiology of this condition, which may identify novel targets for future research on DM-PAD." (PMID 39649955, 2024).
dyslipidemia (1 paper, 2019). "This suggests that Dennd5b-related dyslipidemia is inherited in an autosomal recessive pattern." (PMID 30837651, 2019).
epilepsy (1 paper, 2024). A brain disorder characterized by episodes of abnormally increased neuronal discharge resulting in transient episodes of sensory or motor neurological dysfunction, or psychic dysfunction. "In this study, we identify de novo missense variants in DENND5B as the cause of a neurodevelopmental disorder with dysmorphism and epilepsy." (PMID 38387458, 2024). "Overall, our findings indicate that DENND5B variants perturb intracellular membrane trafficking pathways and cause a complex neurodevelopmental syndrome with variable epilepsy and white matter involvement." (PMID 38387458, 2024).
Hepatic steatosis (1 paper, 2022). Steatosis is a term used to denote lipid accumulation within hepatocytes. "Additionally, we demonstrated that Dennd5b can impact genes involved in hepatic lipid metabolism and affect hepatic lipid content suggesting a possible influence on conditions involving hepatic steatosis such as non-alcoholic fatty liver disease." (PMID 36243100, 2022). "Furthermore, we observed a significant impact of Dennd5b on diet-induced hepatic steatosis which may be mediated by effects of Dennd5b on expression of genes regulating hepatic lipid metabolism." (PMID 36243100, 2022).
Macrocephaly (1 paper, 2024). Occipitofrontal (head) circumference greater than 97th centile compared to appropriate, age matched, sex-matched normal standards. "The presence of either microcephaly (subject #3) or macrocephaly (subjects #1 and #2) in our cohort may be the result of the different functional impact of DENND5B variants." (PMID 38387458, 2024).
temporal lobe epilepsy (1 paper, 2024). A localization-related (focal) form of epilepsy characterized by recurrent seizures that arise from foci within the temporal lobe, most commonly from its mesial aspect. "DENND5B levels were found to be reduced in the brains of subjects with temporal lobe epilepsy and in two distinct chronic epileptic mouse models (kainic acid [KA] and pentylenetetrazole [PTZ] kindling mice), suggesting that DENND5B expression correlates with epileptogenesis." (PMID 38387458, 2024). "Additionally, the expression of DENND5B was recently reported to be significantly decreased in the brains of individuals with temporal lobe epilepsy and chronic epileptic mouse models." (PMID 38387458, 2024).
type 2 diabetes (1 paper, 2020). "Our results from the blood glucose analysis validated well-established gene loci associated with type 2 diabetes with common SNPs in CDKAL1, SLC30A8, SND1-PAX4, IDE-KIF11-HHEX, CDKN2A-CDKN2B, KCNQ1 and CDC123,33,37,38 and identified a novel locus associated with FBG in DENND5B." (PMID 32355288, 2020).
neurodevelopmental disorder (4 papers, 2023 to 2026). A behavioral and cognitive disorder with onset during the developmental period that involves impaired or aberrant development of intellectual, motor, or social functions. "In this study, we describe a complex neurodevelopmental disorder associated with heterozygous de novo variants in DENND5B, encoding a GEF relevant to the activation of Rab family proteins, which are crucial regulators of intracellular vesicular trafficking." (PMID 38387458, 2024). "Subjects harboring DENND5B variants show clinical features common to these two conditions, especially XLID72, suggesting that the disruption of DENND5B-Rab39 interaction may contribute to the pathogenesis of the DENND5B-related neurodevelopmental disorder." (PMID 38387458, 2024). "Overall, a single functional allele of DENND5B may not be sufficient to guarantee the physiological activity of the protein, supporting a disease model where heterozygous loss-of-function variants cause abnormal membrane trafficking and neurodevelopmental disorder." (PMID 38387458, 2024). "As a result, we identified a dozen candidate genes: TSPAN11 as a potential KS candidate gene, TM7SF3, STK38L, ARNTL2, ERGIC2, TMTC1, DENND5B, and ETFBKMT as candidate genes for the neurodevelopmental disorder, and INTS13, REP15, PPFIBP1, and FAR2 as candidate genes for KS with ID." (PMID 37563198, 2023). "The results identified one potential KS candidate gene (TSPAN11), seven candidate genes for the neurodevelopmental disorder (TM7SF3, STK38L, ARNTL2, ERGIC2, TMTC1, DENND5B, and ETFBKMT), and four candidate genes for KS with ID (INTS13, REP15, PPFIBP1, and FAR2)." (PMID 37034680, 2023).
cancer (1 paper, 2016). A tumor composed of atypical neoplastic, often pleomorphic cells that invade other tissues. "Predicted interacting proteins include DENN/MADD domain containing 5B (DENND5B) and vesicular, overexpressed in cancer, prosurvival protein 1 (VOPP1)." (PMID 27096627, 2016).
DENND5B also shares sentences with these, for which no sentence is quoted: cardiovascular disease (1 paper); Cognitive impairment (1); coronary artery disease (1); developmental delay (1); ductal pancreatic adenocarcinoma (1); Dystonia (1); microcephaly (1); non-alcoholic fatty liver disease (1); Obesity (1); Peripheral Artery Disease (1).